LCN2 (lipocalin 2)
Diseases named in the same sentence as LCN2 in open-access papers (continued):
Sharing a sentence is not in itself a finding about the gene and the disease.
glioma (18 papers, 2012 to 2024). A benign or malignant brain and spinal cord tumor that arises from glial cells (astrocytes, oligodendrocytes, ependymal cells). "Currently, the underlying functions and mechanisms of Lcn2-derived circRNAs, and especially hsa_circ_0088732 in glioma, remain largely undetermined." (PMID 32154171, 2020). "Our previous studies showed that NGAL, coded by Lcn2, is associated with the clinical prognosis of glioma." (PMID 32154171, 2020). "Their research demonstrated that exosomes from primary glioma cells increased LCN2 protein levels through the JAK-STAT3 pathway." (PMID 39126107, 2024). "In conclusion, the study elucidated the role of LCN2 in exosome-mediated BBB penetration in gliomas, thereby facilitating the delivery of nanocapsules." (PMID 39126107, 2024). "Recently, it was shown that glioma-derived exosomes can increase BBB fluidity by increasing lipocalin-2 (LCN2) gene expression, which codes for a transporter protein in HBMEC." (PMID 37958619, 2023). "Our previous study showed that LCN2 gene expression was significantly down-regulated in the phenotypically selected BCNU-resistant C6 glioma cells." (PMID 22942880, 2012). "Further studies such as recombinant LCN2 protein treatment, forced expression, or knockdown of LCN2 gene expression in glioma cells revealed that LCN2 downregulation played a key role in the BCNU resistance of glioma cells." (PMID 22942880, 2012). "Among numerous proteins identified by the proteomic comparison of drug-sensitive and resistant glioma cells, lipocalin 2 (LCN2) and integrin β3 (ITGB3) played a central role in regulating glioma chemosensitivity." (PMID 22942880, 2012). "However, the functions and mechanism of lipocalin-2 (Lcn2)-derived circular RNA (hsa_circ_0088732) in glioma progression remain unclear." (PMID 32154171, 2020). "Among numerous proteins that were up- or down-regulated in drug-resistant glioma cells, lipocalin 2 (LCN2) and integrin β3 (ITGB3) were identified as key proteins that determine the survival and death of glioma cells." (PMID 22942880, 2012). "Taken collectively, previous studies provide the evidence for the pro-apoptotic role of LCN2 and ITGB3 in glioma cells." (PMID 22942880, 2012). "Expression of LCN2, ITGB3, and other specific proteins should also be evaluated in glioma tissues of the patients in future studies." (PMID 22942880, 2012). "LCN2 and ITGB3 could be exploited to develop a new therapeutic approach to sensitizing glioma to anticancer drugs." (PMID 22942880, 2012). "LCN2, ITGB3, and other proteins identified by proteomic analysis of glioma chemoresistance may help overcome drug resistance of glioma and improve clinical outcomes of patients." (PMID 22942880, 2012). "LCN2, ITGB3, and other proteins identified by proteomic analysis could be utilized to overcome glioma chemoresistance." (PMID 22942880, 2012).
malaria (18 papers, 2014 to 2025). Malaria is a serious and sometimes fatal disease caused by a parasite that commonly infects a certain type of mosquito which feeds on humans. "In our analyses, IL1R2, LCN2, LTF, and MMP8 were associated with all SM subgroup comparisons to uncomplicated malaria." (PMID 40383794, 2025). "In 2014, Huang and colleagues conducted a proteomic discovery study in 390 Gambian children and identified a panel of two biomarkers (haptoglobin and lipocalin-2) to discriminate acute respiratory infection from severe malaria with respiratory distress." (PMID 30348160, 2018). "The combination of haptoglobin and lipocalin-2 discriminated acute respiratory distress from malaria with high sensitivity and specificity (area under the ROC curve of 99% in Gambian children and 82% in Kenyan children)." (PMID 30348160, 2018). "Malaria severity in pre-anemic mice was exacerbated as denoted by the increased parasitemia and markers of liver injury (serum total bile acids [TBA], alanine transaminase [ALT]), multi-organ injury (aspartate transaminase [AST]) and inflammation (lipocalin 2 [Lcn2], serum amyloid A [SAA])." (PMID 40590713, 2025). "In light of the reported association with septic shock, our associations of elevated IL1R2, LCN2, LTF, MMP8, and OLMF4 in SM subtypes compared to uncomplicated controls may reflect a general signature of the inflammatory reaction to severe infection and may not represent a malaria-specific pathway." (PMID 40383794, 2025).
non-alcoholic steatohepatitis (18 papers, 2013 to 2025). "In animal models of metabolic inflammation, T2DM, or nonalcoholic steatohepatitis, increased LCN2 expression promotes inflammation through the recruitment of inflammatory cells and induction of proinflammatory cytokines." (PMID 36967480, 2023). "In nonalcoholic steatohepatitis, elevated Lcn2 induces neuroinflammation through the release of HMGB1, resulting in blood–brain barrier dysfunction." (PMID 36835151, 2023). "In particular, neutrophils are likely involved in stimulating macrophage activity through the production of soluble LCN2 that is required for efficient non-alcoholic steatohepatitis healing." (PMID 34844610, 2021). "Previous work from others has shown that LCN2 exacerbates steatohepatitis in two animal models of non-alcoholic steatohepatitis by promoting neutrophil-macrophage crosstalk." (PMID 32718038, 2020). "LCN-2 was upregulated in the liver with non-alcoholic steatohepatitis (NASH), especially around inflammatory cell clusters." (PMID 32982804, 2020). "In a nonalcoholic steatohepatitis (NASH) model, high circulatory LCN2 activated 24p3R in the brain and induced the release of high mobility group box 1 (HMGB1)." (PMID 37353794, 2023). "LCN-2 was up-regulated in the livers of fatty liver Shionogi (FLS) mice, an animal model for non-alcoholic steatohepatitis (NASH)." (PMID 35056647, 2022). "In a recent study using mice with diet-induced non-alcoholic steatohepatitis (NASH), the genetic depletion of LCN2 substantially reduced hepatic injury, pro-inflammatory gene expression, and neutrophil and macrophage infiltration." (PMID 32544571, 2020). "In the current study, using a murine model of progressive MAFLD pathology that represents closely nonalcoholic steatohepatitis (NASH), we show that there was a marked increase of Lcn2 in systemic circulation and in diseased livers." (PMID 32622362, 2020). "However, in non-pathogen-driven inflammatory conditions such as non-alcoholic steatohepatitis (NASH) and alcoholic steatohepatitis (ASH), LCN2 plays detrimental roles in the liver through neutrophil infiltration." (PMID 34518636, 2021). "We tested whether the absence of Lipocalin-2 (LCN2) could dysregulate the phosphatidylinositol 3-kinase/protein kinase B (PI3K-PKB) pathway and hepatic homeostasis in Non-Alcoholic-Steatohepatitis (NASH)." (PMID 28725667, 2017).
liver cancer (17 papers, 2015 to 2025). An epithelial or non-epithelial malignant neoplasm that arises from the liver. "Yao and coworkers show that the loss of leukemia inhibitory factor receptor in liver cancer activated NF-κB, which upregulates the iron-sequestering protein lipocalin-2 (LCN2), thereby decreasing ferroptosis sensitivity." (PMID 39372215, 2024). "The implication of LCN2 in the mechanism of Sorafenib susceptibility in liver cancer has been discovered a few years ago." (PMID 33799862, 2021). "Strikingly, either p65 shRNA or Lcn2 shRNA blocked liver tumorigenesis induced by hepatocyte-specific knockout of Lifr, suggesting that loss of Lifr promotes liver cancer development through, at least in part, NF-κB and Lcn2." (PMID 34921145, 2021). "LCN2/Twist1 signaling pathway was associated with liver cancer." (PMID 32272958, 2020). "On the other side, LCN2 is secreted into the serum from liver cancer tissue in human beings and mice." (PMID 34954190, 2022). "This is one of the first studies which connects LCN2 to treatment sensitivity and marks it as a possible therapeutic target of liver cancer." (PMID 33799862, 2021). "We recently reviewed the potential roles of LCN2 in diagnosis and prognosis in prostate, pulmonary and hepatic cancer." (PMID 30893876, 2019). "In the current study, we show in humans and mice that LCN2 is secreted into the serum from liver cancer tissue." (PMID 30893876, 2019). "It has been reported that upregulation of LCN2 could deplete iron and weaken sensitivity to ferroptosis inducers in liver cancer cells." (PMID 40313933, 2025). "Also, Lcn-2 expression substantially inhibited liver metastasis upon inoculation of nude BALB/c mice with a human highly metastatic liver cancer cell line, KM12SM, thereby proving that Lcn-2 can also have a negative effect on tumor development." (PMID 37958332, 2023). "LCN2 seems to have an anti-tumorigenic effect on liver cancer cells." (PMID 33799862, 2021). "Thus, anti-LCN2 therapy is a promising way to improve liver cancer treatment by targeting ferroptosis." (PMID 34921145, 2021). "However, several other studies suggest that LCN2 has the opposite effect on liver cancer cells." (PMID 33799862, 2021). "In this study, we first found that curcumin induced changes in the expression of CYP1A1, HMGCS2, HMOX1, LCN2, and MTTP, which are enriched in metal ion homeostasis, in all three liver cancer cell lines." (PMID 36838613, 2023). "Indeed, overexpression of LIFR sensitized PLC/PRF/5 cells to erastin or sorafenib, which could be reversed by co-treatment with liproxstatin-1, DFO, or purified LCN2 protein, indicating that LIFR sensitizes liver cancer cells to ferroptosis inducers through iron and LCN2." (PMID 34921145, 2021).
oral squamous cell carcinoma (17 papers, 2018 to 2025). "High LCN2 expression was positively associated with differentiation, lymph node metastasis, and T staging and predicted a poor prognosis in oral squamous cell carcinoma (OSCC) patients." (PMID 31819048, 2019). "The combination of vitamin D and cisplatin showed synergistic regulation of the NF-κB pathway, modulated by lipocalin-2 (LCN2) in oral squamous cell carcinoma." (PMID 34361037, 2021). "In oral squamous cell carcinoma, the knockdown of LCN2 correlated with increased cancer cell malignant potential and resistance against chemotherapy with upregulated MMP-9 expression." (PMID 34062746, 2021). "Downregulation of LCN2 has been reported in oral squamous cell carcinoma." (PMID 34903175, 2021). "Furthermore, LCN2 suppresses tumor metastasis in osteosarcoma and oral squamous cell carcinoma." (PMID 36428800, 2022). "Lcn-2 was also identified as an important suppressor of radiotherapy success in oral squamous cell carcinoma (OSCC), whereby radiated Ca9-22 cells showed the strongest increase in Lcn-2 expression." (PMID 37958332, 2023).
vascular dementia (17 papers, 2019 to 2025). A degenerative vascular disorder affecting the brain. "Recently, a growing body of evidence has indicated that the LCN2 was associated with AD pathogenesis, vascular dementia, and other neurodegenerative dementias." (PMID 34903175, 2021). "Furthermore, Lcn2 promotes neuronal loss and hippocampal-dependent memory deficits in a mouse model of vascular dementia." (PMID 35820938, 2022). "High levels of LCN2 were also found in the cerebrospinal fluid of patients with vascular dementia, a condition characterized by changes in memory and behavior as a consequence of pathological changes in the brain vasculature." (PMID 37496672, 2023). "In support of these data, LCN2 was increased in the CNS and CSF in patients with vascular dementia, correlating with reduced expression of TJ proteins and increased BBB permeability, thus suggesting a role for LCN2 in BBB dysfunction." (PMID 36034148, 2022). "Serum and CSF LCN2 levels were higher in patients with vascular dementia and increased CSF LCN2 positively correlated with age-related white matter alterations." (PMID 34829528, 2021). "A recent report also suggests that lipocalin 2 secreted from reactive astrocytes in the cerebrospinal fluid is a promising biochemical marker candidate for the differential diagnosis of vascular dementia and neurodegenerative dementias." (PMID 34565419, 2021). "The 3xTg-AD model showed an accentuated upregulation of Klk6 and Lcn2, which have been evaluated as possible markers of AD and vascular dementia, respectively." (PMID 34702310, 2021). "Clinically, lipocalin-2 in cerebrospinal fluid is a convincing biomarker for the differential diagnosis between vascular dementia and neurodegenerative dementias." (PMID 35010945, 2021). "A previous animal study illustrated that VEGF-A and its upstream mediator lipocalin-2 play a critical role in the BBB breakdown in hippocampus of the vascular dementia (VaD)." (PMID 31039131, 2019). "Patients with MCI and vascular dementia show increased levels of Lipocalin 2 (Lcn2) in the CSF." (PMID 33921556, 2021).
dementia (16 papers, 2017 to 2025). Loss of intellectual abilities interfering with an individual's social and occupational functions. "The fact that dementia is also linked to multiple mechanisms related to LCN2, such as inflammatory responses, iron metabolism, and cellular apoptosis, highlights the importance of the relationship between LCN2 and the neuropathology of dementia." (PMID 33945675, 2021). "Given the significant evidence supporting the involvement of LCN2 in the demented brain, we believe that the level of LCN2 in the brain is a critical factor in the regulation of risk factors for dementia." (PMID 33945675, 2021). "Here, we emphasize that LCN2 has crucial pathogenic roles in dementia through the regulation of iron homeostasis, neuroinflammation, and insulin resistance." (PMID 33945675, 2021). "Further investigations into the mechanism(s) underlying the link between iron homeostasis and LCN2 in the brain are needed, as iron imbalance is a critical problem leading to memory loss in patients with dementia." (PMID 33945675, 2021). "Here, the authors show that vascular dementia is associated with increased lipocalin-2 in cerebrospinal fluid, compared to controls and patients with other forms of dementia." (PMID 32001681, 2020). "The presented clinical data indicate that CSF LCN2 is a marker for dementia associated with VBI and that it has the potential to become a complementary tool in the differential diagnosis of VaD and AD." (PMID 32001681, 2020). "However, it has also been reported that astrocytes can secrete LCN2 in response to neuroinflammation, a condition that can occur in T2D and has been associated with dementia." (PMID 39808380, 2025). "The results from cohort 1 show that LCN2 levels might allow accurate differentiation between VaD and neurological controls as well as all other investigated causes of dementia." (PMID 32001681, 2020). "Future research should also investigate the combined predictive value of LCN2 alongside other dementia‐related blood biomarkers, such as neurofilament light chain (NfL), to enhance diagnostic accuracy." (PMID 40365739, 2025). "Here, we aimed to investigate plasma LCN2 in the context of the differential diagnoses of dementia and its utility as an independent biomarker by analyzing associations with biomarkers of AD-related pathology as well as with clinical data in AD patients." (PMID 35027079, 2022). "Here, we review recent evidence on the regulatory role of lipocalin 2 (LCN2) in dementia from various perspectives." (PMID 33945675, 2021). "Taken together, the existing evidence suggests that LCN2 is key to the regulation of excessive iron accumulation and inflammation in the brain of dementia patients." (PMID 33945675, 2021). "Here, we review the evidence for the involvement of LCN2 in dementia, focusing on neuroinflammation, iron accumulation, and metabolic alterations." (PMID 33945675, 2021). "The onset and progression of dementia are influenced by a variety of LCN2‐mediated mechanisms including inflammation, insulin resistance, iron accumulation, immune response, neuronal cell damage, and glia dysfunction." (PMID 33945675, 2021). "To summarize, LCN2 contributes to inflammatory responses and regulates various cell signaling pathways, affecting neurons and glia in the brains of patients with dementia." (PMID 33945675, 2021). "Taken together, LCN2 is a promising therapeutic target with which to address the neuropathology of dementia." (PMID 33945675, 2021). "The relationship between the level of LCN2 and the pathological progression of dementia has been reported in previous studies." (PMID 33945675, 2021). "Moreover, a recent study considered lipocalin-2 to be a promising therapeutic target in the management of dementia." (PMID 36558562, 2022).
dementia (continued). "Other blood biomarkers that could be elevated in the preclinical stage of dementia, such as insulin, fibroblast growth factor 21, lipocalin-2, or trimethylamine N-oxide may need to be considered to help increase the discriminative properties." (PMID 36292406, 2022). "Below, we review the roles of LCN2 in dementia from various perspectives." (PMID 33945675, 2021). "The role of LCN2 in neuronal cell damage in the brain of dementia patients." (PMID 33945675, 2021). "Furthermore, LCN2 is involved in the accumulation of iron that occurs within brain neurons of patients with dementia and is related to cognitive dysfunction." (PMID 33945675, 2021). "Based on these findings, we suspect that the levels of LCN2 may differ across the various models of dementia due to the difficulties in measuring the levels of LCN2 during the progress of dementia." (PMID 33945675, 2021). "Especially in cohort 1, many samples were collected in the framework of differential diagnosis of atypical or rapidly progressive dementia, which may explain higher LCN2 levels compared to the other cohorts." (PMID 32001681, 2020). "However, LCN2 seems to differentiate VaD from other forms of dementia better than what has been shown for Qalb30,31,34." (PMID 32001681, 2020). "Appropriate modulation of LCN2 may enhance the neuropathology of dementia." (PMID 33945675, 2021). "Therefore, the modulation of LCN2 levels in the brain may be key to reducing pro‐inflammatory responses that occur in the brain of individuals with dementia." (PMID 33945675, 2021). "The modulation of LCN2 levels may contribute to the attenuation of the neuropathology of dementia, given that recent research focused on the chemotherapy in CNS disease including dementia as well as brain tumor." (PMID 33945675, 2021). "Therefore, we compared CSF LCN2 levels in different forms of dementia, VBI, and controls." (PMID 32001681, 2020). "Thus, we emphasize that LCN2 may be a critical target for the treatment and prevention of dementia." (PMID 33945675, 2021). "Furthermore, LCN2 may modulate diverse pathological mechanisms involved in dementia." (PMID 33945675, 2021). "Our results show that CSF LCN2 is elevated in patients with VaD compared to controls, cognitively unimpaired patients with VBI, and other forms of dementia." (PMID 32001681, 2020). "Comorbidities that might influence LCN2 levels were only excluded in HC, MCI, and AD groups but may potentially be present in other dementia groups." (PMID 35027079, 2022). "The pathophysiological background of plasma LCN2 and its alterations in body fluids of dementia patients is not deciphered, though." (PMID 35027079, 2022). "The highest mean concentrations of plasma LCN2 were observed in the VaD group (mean: 135.0 ng/ml, SD ± 120.3) but the differences versus other groups, as well as differences between other dementia groups and HC, were not statistically significant." (PMID 35027079, 2022). "In a separate statistical model including Mini Mental Status Examination (MMSE) score in the group of covariates, VaD groups showed significantly higher LCN2 levels than AD groups in all four cohorts, indicating that dementia stage does not significantly alter the results." (PMID 32001681, 2020).